ANGPTL2 (angiopoietin like 2)
Diseases named in the same sentence as ANGPTL2 in open-access papers (continued):
Sharing a sentence is not in itself a finding about the gene and the disease.
cardiac hypertrophy (3 papers, 2016 to 2024). "Angptl2 KO mice also showed decreased fractional shortening, but to a lesser degree, and retained adaptive cardiac hypertrophy without ventricular dilatation." (PMID 27677409, 2016).
diabetic nephropathy (3 papers, 2017 to 2024). "Similarly, elevated circulating ANGPTL2 levels in association with albuminuria were reported in patients with diabetic nephropathy." (PMID 29138671, 2017). "ANGPTL2 is a proangiogenic factor, and this may explain the abnormal vessel growth observed in diabetic nephropathy." (PMID 29138671, 2017). "ANGPTL2, previously associated with major adverse cardiovascular events, was considered as a marker of macrovascular disease, while TNFR1, which proved to be consistently associated with progression of diabetic kidney disease, was considered as a marker of microvascular disease." (PMID 29879997, 2018). "Proliferative DR (but not other components of microvascular disease such as diabetic kidney disease) and serum concentration of ANGPTL2 were independent predictors for minor amputation." (PMID 29879997, 2018).
hepatocellular carcinoma (3 papers, 2015 to 2026). A malignant tumor that arises from hepatocytes. "Furthermore, we assessed the effects of enforced expression of Ad-ANGPTL2 and Ad-LacZ on Akt phosphorylation in 3T3L1 adipocytes, C2C12 murine myoblasts, and HepG2 hepatocellular carcinoma cells, which did not effect on Akt phosphorylation." (PMID 26132105, 2015).
liver fibrosis (3 papers, 2017 to 2019). "Angptl2 levels were significantly associated with liver fibrosis stages (P = 0.02)." (PMID 31385666, 2019). "In this study, Angptl2 exhibited association with liver fibrosis in hepatitis B patients." (PMID 28962551, 2017). "In our study, we found that despite the normal levels of ALT, the Angptl2 serum levels were greater with higher liver fibrosis stages." (PMID 31385666, 2019). "With all this evidence, it seems reasonable to assume that Angptl2 plays a significant role in liver fibrosis in HBV patients." (PMID 31385666, 2019). "We found that despite normal ALT levels, the Angptl2 concentrations were greater with hepatic fibrosis progression." (PMID 31385666, 2019). "Angptl2 proved that it can be used successfully as an indicator of liver fibrosis in many ways." (PMID 31385666, 2019). "In this study, we hypothesized that Angptl2 participates in hepatic fibrogenesis in chronic liver disease and would be as a potential biomarker for diagnosis of liver fibrosis." (PMID 28962551, 2017). "The basic research of the relationship between Angptl2 and liver fibrosis is currently in progress." (PMID 27605044, 2017).
non-small cell lung carcinoma (3 papers, 2018 to 2021). A group of at least three distinct histological types of lung cancer, including non-small cell squamous cell carcinoma, adenocarcinoma, and large cell carcinoma. "Since serum ANGPTL2 levels were significantly increased in patients with non-small cell lung cancer, it could serve as a novel potential diagnostic and prognostic biomarker." (PMID 34447409, 2021). "ANGPTL2 also promotes M2 polarization of macrophages in non-small cell lung cancer." (PMID 33197890, 2020). "It has been reported that LILRB2 and ANGPTL2/ANGPTL5 were co-expressed in cancer cell lines and in primary culture of non-small cell lung cancer NSCLC." (PMID 29389861, 2018).
pancreatic cancer (3 papers, 2017 to 2020). "Besides, ANGPTL2 was proved to be among the pro‐inflammatory factors overexpressed in pancreatic cancer (PC) cells which led to epithelial‐to‐mesenchymal transition (EMT) and resistance of anti‐VEGF treatment." (PMID 32410376, 2020). "In pancreatic cancer cell lines, an autocrine loop between LILRB2 and its ligand ANGPTL2 has also been demonstrated, leading to early stages of cancer, suggesting again a local action of ANGPTL2." (PMID 29138671, 2017). "The binding of ANGPTL2 to LILRB2 might be restricted to HSC, platelets, and some pancreatic cancer cells." (PMID 29138671, 2017).
polycystic ovary syndrome (3 papers, 2018 to 2022). A disorder that manifests as multiple cysts on the ovaries. "This study investigated the expression of angiopoietin-like protein 2 (ANGPTL2) in the tissues of rat models of polycystic ovary syndrome (PCOS) and its correlation with PCOS." (PMID 32988397, 2020).
renal fibrosis (3 papers, 2017 to 2026). A final common manifestation of a wide variety of chronic kidney diseases characterized by glomerulosclerosis and tubulointerstitial fibrosis. "Given that perirenal adipose tissue (PRAT) can influence kidney function, to better understand the protective role of ANGPTL2 deficiency against HFD‐induced renal fibrosis, we examined a potential role of ANGPTL2 in PRAT." (PMID 41508557, 2026). "Activated Angptl2 downregulated autophagy, increased pro-inflammatory factors, accelerated renal fibrosis by activating the MKKK-ERK-Nrf1 pathway, which was completely reversed by Angptl2 knockdown in a diabetic rat model." (PMID 32724454, 2020). "More importantly, ANGPTL2 promotes renal fibrosis by activating the expression of the growth factor TGFβ1 through α5β1 integrin-mediated activation of extracellular signal-regulated kinase." (PMID 29138671, 2017).
thyroid cancer (3 papers, 2019 to 2021). "ANGPTL2 expression is associated with a poor prognosis; it can increase the proliferation of thyroid cancer cells and promote their migration and invasion." (PMID 34049534, 2021). "Correlations of ANGPTL2 expression levels with proliferation, migration, and metastasis of thyroid cancer were assessed with the TCGA data set and analyzed by gene set enrichment analysis." (PMID 31384179, 2019). "Survival analysis was performed using the thyroid cancer database in K–M Plotter to detect correlations between survival time and ANGPTL2 levels." (PMID 31384179, 2019). "Putting together, these data demonstrated ANGPTL2 expression to promote thyroid cancer cell proliferation." (PMID 31384179, 2019). "The ANGPTL2 mRNA in normal thyroid tissue and thyroid cancer tissue with different severity stages (I, II, III, IV) were divided into ANGPTL2 high/low expression groups according to median respectively." (PMID 31384179, 2019). "To investigate the role of ANGPTL2 in thyroid cancer metastasis, we evaluated migration of thyroid cancer cells by scratch." (PMID 31384179, 2019). "Receiver operating characteristic analysis was used to evaluate the utility of ANGPTL2 as a biomarker for prediction of thyroid cancer." (PMID 31384179, 2019). "This study evaluated 36 patients with PTC and found the protein level of ANGPTL2 was higher in thyroid cancer tissue than adjacent normal thyroid tissue." (PMID 31384179, 2019). "The ratio of case number with ANGPTL2 high/low mRNA level from different thyroid cancer stages was compared." (PMID 31384179, 2019). "The biological effect of ANGPTL2 on thyroid cancer cell proliferation and metastasis was investigated by the Cell Counting Kit-8 (CCK8) assay, cell scratch test, and transwell assay." (PMID 31384179, 2019). "So far, no specific analysis has been done for the expression and function of ANGPTL2 on thyroid cancer." (PMID 31384179, 2019). "Thus, ANGPTL2 mRNA level from TCGA’s RNA-seq data in thyroid cancer and adjacent tissue was analyzed." (PMID 31384179, 2019). "ANGPTL2 promoted and enhanced proliferation, metastasis, and invasion of thyroid cancer cells." (PMID 31384179, 2019). "Furthermore, the utility of ANGPTL2 as a predictive biomarker for thyroid cancer was evaluated by receiver operating characteristic (ROC) analysis with the data from TCGA." (PMID 31384179, 2019). "We have found that ANGPTL2 protein level was positively correlated with tumor volume and ANGPTL2 mRNA or protein level were increased along with cancer severity stage, so the effects of ANGPTL2 expression on thyroid cancer cell proliferation, migration and invasion were investigated." (PMID 31384179, 2019). "Taking together, the level of ANGPTL2 may serve as a prognostic indicator for patients with thyroid cancer." (PMID 31384179, 2019). "ANGPTL2 may be considered as a potential biomarker for diagnosis and prognosis of thyroid cancer patients." (PMID 31384179, 2019). "To further verify whether the mRNA levels of ANGPTL2 are related to thyroid cancer cell proliferation and decreased in thyroid cancer migration/invasion in clinical specimens, we analyzed the mRNA levels of ANGPTL2 in TCGA data base according to TNM stage." (PMID 31384179, 2019). "In order to understand the role of ANGPTL2 in thyroid cancer cell proliferation, TPC-1 thyroid cancer cells were transfected with an expression construct carrying either cDNA ANGPTL2 or siRNA-ANGPTL2 respectively, which results in either overexpression or down regulation of ANGPTL2 in TPC-1." (PMID 31384179, 2019). "Results showed that ANGPTL2 mRNA level was significantly upregulated in thyroid cancer cell comparing to adjacent non-tumor thyroid tissue cell (p < 0.0001)." (PMID 31384179, 2019).
thyroid cancer (continued). "Nevertheless, lacking the studies on the correlation between ANGPTL2 expression level, and proliferative/invasive ability in thyroid cancer, leave a gap for further deep investigation about the possibility of ANGPTL2 being as potential molecular target therapeutically." (PMID 31384179, 2019).
acne (2 papers, 2024). An inflammatory process of the sebaceous glands which is characterized by comedones, nodules, papules and/or pustules on the skin. "Moreover, the function of the other genes, including FAS, SDC1, ANGPTL2, IL-15RA, INHBA, and OSMR in lymphocytes, keratinocytes, fibroblasts, and smooth muscle, are yet to be explored, suggesting that acne involves not only the skin’s surface but also a wider systemic dysregulation." (PMID 38854033, 2024).
acute myocardial infarction (2 papers, 2024 to 2025). Necrosis of the myocardium, as a result of interruption of the blood supply to the area. "In conclusion, elevated ANGPTL2 expression in plasma and platelets promoted SR of obstructed coronary arteries in patients with acute myocardial infarction." (PMID 38880861, 2025). "On the other hand, ANGPTL2 has been proposed to promote physiological remodeling and maintenance of tissue homeostasis; for example, administration of resident cardiac cells expressing ANGPTL2 in rats after myocardial infarction improved LV function and increased neovascularization." (PMID 38426206, 2024).
Alzheimer disease (2 papers, 2021 to 2024). A progressive, neurodegenerative disease characterized by loss of function and death of nerve cells in several areas of the brain leading to loss of cognitive function such as memory and language. "Inflammatory cytokines TNF-α and IL-6 secreted by microglial M1 macrophages and Angptl2 have been shown to induce neuroinflammation and participate in the progression of neurodegenerative diseases, such as Alzheimer’s disease." (PMID 38785563, 2024).
aortic valve stenosis (2 papers, 2022 to 2024). Aortic valve stenosis (AVS) is a condition characterized by narrowing of the heart's aortic valve opening. "Mice knockdown for Angiopoietin-like 2 (Angptl2) exhibit spontaneous aortic valve stenosis associated with a decrease in Notch signalling and an imbalance in cell apoptosis, senescence and proliferation during embryonic valve remodelling stage." (PMID 36414704, 2022). "Indeed, in adult mice knocked down (KD) for ANGPTL2, we recently reported a mild left ventricular (LV) dysfunction originating from a congenital aortic valve stenosis, demonstrating that ANGPTL2 is essential to cardiac development and function." (PMID 38426206, 2024).
Arthritis (2 papers, 2023 to 2026). Inflammation of a joint. "The relationship between ANGPTL2 expression and other irAEs, such as arthritis, dermatitis, pneumonitis, and colitis, warrants further investigation." (PMID 37736764, 2023). "ANGPTL-related signaling patterns differed among arthritis subtypes, with ANGPTL4 more prominent in OA and PsA and ANGPTL2 more frequently in RA-related transcriptional programs." (PMID 41751295, 2026).
autoimmune myocarditis (2 papers, 2023 to 2026). Autoimmune myocarditis is an autoimmune disease that affects the heart. "To assess a potential ANGPTL2 function in autoimmune myocarditis, we subjected both Angptl2-deficient (Angptl2-/-) and WT mice to the EAM only model and assessed development of inflammation 10 days later." (PMID 37736764, 2023). "Here, we demonstrate that ANGPTL2 deficiency attenuates ICI-related autoimmune myocarditis, a condition mediated by T cells." (PMID 37736764, 2023). "In addition, give our finding that ANGPTL2 activity underlies ICI-related autoimmune myocarditis, assessing a factor that serves as a causal factor of cardiotoxicity prior to ICI treatment could predict future development of irAE." (PMID 37736764, 2023). "By contrast, in the EAM + ICI model, we observed significantly increased serum ANGPTL2 levels at days 10 and 20, suggesting that ANGPTL2 activity is associated with ICI-related autoimmune myocarditis." (PMID 37736764, 2023). "Here, we demonstrate that levels of circulating ANGPTL2 protein increased in a murine ICI-related autoimmune myocarditis model." (PMID 37736764, 2023). "Here, we report that cardiac fibroblast-derived ANGPTL2 plays a role in ICI-related autoimmune myocarditis by enhancing chemokine-induced recruitment of T cells." (PMID 37736764, 2023). "Cardiac fibroblast-derived ANGPTL2 plays a role in immune checkpoint inhibitors -related autoimmune myocarditis by enhancing chemokine-induced recruitment of T cells." (PMID 37736764, 2023). "We conclude that cardiac myofibroblast-derived ANGPTL2 may enhance ICI-related autoimmune myocarditis." (PMID 37736764, 2023). "Here, we investigate the function of Angiopoietin-like protein 2 (ANGPTL2), a potential inflammatory mediator, in a mouse model of ICI-related autoimmune myocarditis." (PMID 37736764, 2023).
breast tumor (2 papers, 2015 to 2016). "We also found that ETS1-dependent transcription was important for ANGPTL2-induced CXCR4 expression and that ANGPTL2 increased breast tumor cell invasiveness by activating ERK and MMP-13 expression." (PMID 25773070, 2015). "In the present study, we performed RNA sequence analysis of MDA-MB231 cells harboring ANGPTL2 knockdown (MB231/miANGPTL2) and found that, relative to control (MB231/miLacZ) cells, CXCR4 expression significantly decreased, suggesting that ANGPTL2 contributes to CXCR4 expression in breast tumor cells." (PMID 25773070, 2015). "We conclude that tumor cell-derived ANGPTL2 may increase bone metastasis by enhancing breast tumor cell responsiveness to CXCL12 signaling through up-regulation of tumor cell CXCR4 expression." (PMID 25773070, 2015). "To determine what factors downstream of ANGPTL2 might promote metastasis, we compared transcripts in ANGPTL2 knockdown human breast tumor MB231 cells to those in control MB231 cells using an RNA sequencing strategy." (PMID 25773070, 2015).
chronic hepatitis B (2 papers, 2017 to 2019). "The last limitation was that the Angptl2 levels in patients with F3–6 were overlapped with those in patients with F0–2, suggesting the difficulties to set up a cut-off level to estimate the fibrosis stages in chronic hepatitis B patients." (PMID 28962551, 2017). "This is an advantage to Angptl2, as LSM results could be considered mainly false negatives because of macronodular cirrhosis, which is more common in chronic hepatitis B." (PMID 31385666, 2019).
colitis (2 papers, 2017 to 2023). Inflammation of the colon. "In this study, we show that ISEMF‐derived ANGPTL2 is important to regulate epithelial wound repair in models of DSS‐induced colitis." (PMID 28043948, 2017).
diabetic foot ulcer (2 papers, 2020 to 2024). "Similarly, patients with diabetic foot ulcer (DFU) exhibited elevated ANGPTL2 levels when compared to subjects with T2DM only (T2DM vs. DFU: 4.221 ± 1.301 vs. 6.561 ± 2.335 μg/L, p < 0.0001)." (PMID 39350883, 2024). "However, no data regarding the relationship between ANGPTL2 and diabetic foot ulcers (DFUs) are available." (PMID 33256685, 2020).
diabetic retinopathy (2 papers, 2018 to 2024). "History of PAD (HR 4.37 95% CI [2.11–9.07]; p < 0.001), severe diabetic retinopathy (2.69 [1.31–5.57]; p = 0.0073), male gender (10.12 [2.41–42.56]; p = 0.0016) and serum ANGPTL2 concentrations (1.25 [1.08–1.45]; p = 0.0025) were associated with minor amputation outcome." (PMID 29879997, 2018). "In contrast to that study, we found a significant positive correlation between VEGF-A and ANGPTL2 in the serum of diabetic patients with and without diabetic retinopathy." (PMID 39350883, 2024). "A former study was done on serum ANGPTL2 in diabetic retinopathy patients with and without macular edema." (PMID 39350883, 2024).
dilated cardiomyopathy (2 papers, 2017 to 2021). Cardiomyopathy which is characterized by dilation and contractile dysfunction of the left and right ventricles. "Circulating ANGPTL2 levels positively correlate with cardiac dysfunction in patients with dilated cardiomyopathy." (PMID 34737791, 2021).
interstitial pulmonary fibrosis (2 papers, 2021 to 2025). "Conversely, in a mouse model of lung fibrosis, ANGPTL2 was shown to have a protective effect against the disease." (PMID 40243889, 2025).
ischemic stroke (2 papers, 2016 to 2018). A stroke disorder caused by obstruction of blood flow to the brain, due to thrombotic (local blood clot formation) or embolic (due to a blood clot or other material traveling from another site) event. "Infiltrated macrophage-derived ANGPTL2 enhanced inflammatory responses and was associated with severe brain tissue damage in the acute phase of ischemic stroke." (PMID 27861531, 2016). "LncRNA TCONS_00097976 is connected to angiogenesis-related miR-92b-3p and angiogenesis-related genes Esm1, Angptl2, and Stat3, which have been reported differently expressed in ischemic stroke." (PMID 29516010, 2018). "To determine ANGPTL2 function in ischemic stroke, we compared wild-type (WT) and systemic Angptl2 knockout (KO) mice in terms of degree of cerebral injury in the transient MCAO model." (PMID 27861531, 2016). "Therefore, lowering the cytotoxic effects of TNF-toxic and IL-1β in the CNS by ANGPTL2 suppression may serve as an attractive therapeutic option in the acute phase of ischemic stroke." (PMID 27861531, 2016). "ANGPTL2 levels significantly increased in ischemic brain 24 hours after MCAO, likely contributing to neuronal injury seen in the acute phase of ischemic stroke." (PMID 27861531, 2016).
liver cirrhosis (2 papers, 2017 to 2019). "Additionally, high levels of Angptl2 protein were positively correlated with liver cirrhosis in HCC patients." (PMID 31385666, 2019). "Additionally, high levels of Angptl2 protein positively was correlated with histological grade, and liver cirrhosis HCC patients." (PMID 28962551, 2017).
mastitis (2 papers, 2022 to 2024). Inflammation of breast tissue during lactation or postpartum due to an obstructed duct or infection. "Kaempferol can reduce the expression of IL-6 and TNF-α and ANGPTL2 in cells, prevent the occurrence of mastitis in mice, inhibit the phosphorylation of NF-κB P65 subunit and the degradation of IκBα, and play a therapeutic role in mastitis." (PMID 35757473, 2022). "Kaempferol suppressed phosphorylation of the NF-κB p65 subunit and the degradation of its inhibitor, IκBα, in the NF-κB signal pathway for the treatment of mastitis; this was accompanied by decreased myeloperoxidase (MPO) production and ANGPTL2 expression, as well as a reduction in TNF-α and IL-6." (PMID 38630770, 2024).
myocarditis (2 papers, 2023 to 2025). Myocarditis is a condition that is characterized by inflammation of the heart muscle (myocardium). "We next addressed potential immunoregulatory mechanisms underlying ANGPTL2 activity in the context of ICI-related myocarditis." (PMID 37736764, 2023).